CDKN2A (cyclin dependent kinase inhibitor 2A)
Diseases named in the same sentence as CDKN2A in open-access papers (continued):
Sharing a sentence is not in itself a finding about the gene and the disease.
glioblastoma (continued). "It is unclear how NF1 could provide a protective prognostic effect in CDKN2Aint patients, but this dichotomous impact of NF1 on survival in CDKN2A stratified patients suggests that CDKN2A may significantly modulate NF1 activity in IDHwt glioblastoma patients." (PMID 36380219, 2022). "Importantly, multiple studies suggested that co-deletions of Cdkn2c and Cdkn2a/b/ARF observed in some human cancers such as glioblastoma are responsible for worsened tumor severity." (PMID 33078209, 2021). "In IDH-wildtype glioblastomas (n = 2,072), we identified distinct tumor clusters based on immune cell proportion and demonstrated an association with oncogenic alterations such as EGFR amplification and CDKN2A/B homozygous deletion." (PMID 34496929, 2021). "Moreover, we will delve deeper into genotyping our model for numerous interests, including CDKN2A deletion, EGFR amplification, IDH1/2, FGFR-TACC3, and H3K27M mutation because of their prevalence in human glioblastoma." (PMID 34884748, 2021). "The FGFR3 glioblastoma cases exhibited the most common mutations found in IDH-wild-type glioblastoma, with CDKN2A homozygous loss in all cases, followed by PTEN mutations with LOH and CDKN2B homozygous loss, in three cases, and TERT c.124C>T promoter mutation in two cases." (PMID 33853673, 2021). "In glioblastoma with primitive neuronal component, CDKN2A/B is deleted in only 15.9% of samples." (PMID 33876327, 2021). "We aimed to evaluate the clinical outcomes of molecular glioblastoma (mGBM) as compared to histological GBM (hGBM) and to determine the prognostic impact of TERT mutation, EGFR amplification, and CDKN2A/B deletion on isocitrate dehydrogenase (IDH)-wildtype GBM." (PMID 33235995, 2020). "IDH-mutated glioblastomas without CDKN2A homozygous deletion still showed poorer prognosis compared with that of lower grade astrocytomas." (PMID 33228806, 2020). "Furthermore, both cohorts exhibited significant deletion in chromosome 10, one of the major genomic features of glioblastoma, and chromosome 9, harboring CDKN2A and CDKN2B." (PMID 32794373, 2020). "Unlike these, the mutations in SEGA-like glioblastoma occurred in the context of other genetic aberrations present in high-grade neoplasms, including in the CDKN2A/B, PIK3R1, PIK3CA and EGFR genes." (PMID 31258848, 2019). "Moreover, it was found that primary glioblastoma cells retain a functional senescence program despite mutations in the TERT promoter and CDKN2A/B locus." (PMID 29616301, 2018). "Importantly, our study also unravels the epigenetic regulation of CDKN2A in glioblastoma cells." (PMID 38438773, 2024).
glioblastoma (continued). "Jenna K Minami’s team found that knocking down CDKN2A can promote lipid peroxidation in GBM cells, selectively induce tumor ferroptosis, and thereby inhibit the malignant progression of glioblastoma." (PMID 39493751, 2024). "Furthermore, emerging evidence suggests that CDKN2A may play a role in the maintenance of glioblastoma stem cells (GSCs), a subpopulation of cells with self-renewal capacity and pluripotency that contribute to tumor initiation, growth, and therapy resistance." (PMID 38438773, 2024). "Subsequently, studies have also identified CDKN2A/B homozygous deletion as a significant prognostic marker of glioblastoma multiforme (GBM)." (PMID 37190513, 2023). "Moreover, there was a perfect correlation between CDKN2A/2B homozygous loss and decreased RNA expression levels, although decreased levels were also seen in the absence of gene loss in two IDH-wild-type and one IDH-mutant glioblastoma cases." (PMID 34572759, 2021). "It is reported that co-deletion of CDKN2A and CDKN2C confer Palbociclib-sensitivity in glioblastoma and soft tissue sarcoma, demonstrating that amplification of CDK4 benefits from the CDK4/6 inhibitor." (PMID 38369555, 2024). "In the present study, we investigated the prognostic role of CDKN2A homozygous deletion in WHO grade 4 CNS gliomas, including IDH-mutant astrocytoma’s and IDH-wildtype glioblastomas." (PMID 39457569, 2024). "Patient #12, a 54-year-old male diagnosed with glioblastoma (GBM) with the BCR::NTRK2 fusion, PTEN mutation, homozygous deletion of CDKN2A/2B, and TERTp mutation (C228T), refused adjuvant therapy and received palliative care, resulting in death 13 months post-surgery." (PMID 39014476, 2024). "Noteworthy, the alterations of CDKN2A/B in three BMs showed copy number amplification in Case 3, instead of frequency CNV deletion reported in primary glioblastoma." (PMID 37384291, 2023). "Multivariate analysis identified CDKN2A HD as a predictor of significantly shorter PFS and OS in both LGG and glioblastoma in all included studies." (PMID 37504251, 2023). "Demonstrated that G-CIMP’s low methylation profile and CDKN2A/B HD bared an extremely poor prognosis in IDH-mutant astrocytomas, similar to IDH-wildtype glioblastomas." (PMID 37504251, 2023). "In a study of IDH-mutant ‘glioblastomas’ (now known as IDH-mutant grade 4 astrocytomas), CDKN2A/B HD was found to be a poor prognostic factor." (PMID 37504251, 2023).
glioblastoma (continued). "IDH wild-type OT formed cluster C2 and had a genomic profile as typically observed in glioblastomas, characterized by gains of chromosome 7, EGFR amplifications, CDKN2A deletions and losses of chromosome 10." (PMID 27090007, 2016). "In glioblastomas (GBM), the most common alterations were gene amplifications (PDGFRA, KIT, KDR, EGFR, and MET) and deletions (CDKN2A and PTEN)." (PMID 27172220, 2016). "Those genes include EGFR, PDGFRA, FGFR3, PIK3CA, MDM4, CDKN2A/B, PTEN and are all members of the core alterated pathways in glioblastoma controlling key phenotypes such as proliferation, apoptosis and angiogenesis." (PMID 25679508, 2015). "Pairwise comparison between the tumor grades indicated that the relative expression of the CDKN2A and CDKN2B transcripts was approximately 1.3-fold lower in grade IV glioblastoma compared with that in grade II astrocytoma (p<0.001)." (PMID 26317630, 2015). "Deletion of CDKN2A and simultaneous overexpression of CDK4 in mice astrocytes generates high proliferating immortal cells and is also studied as a model for glioblastoma development." (PMID 25954815, 2015). "Focal homozygous deletion of cyclin-dependent kinase inhibitor 2A (CDKN2A) is a frequent finding in EGFR amplified tumors and these, together with the EGFRvIII, are features of the classical transcriptional subtype of glioblastoma." (PMID 25785247, 2015). "Primary glioblastomas exhibit frequent EGFR amplification, homozygous deletion of CDKN2A and p14ARF, CDK4 amplification, MDM2 or MDM4 amplification, RB1 mutation/homozygous deletion, monosomy 10 and PTEN mutation." (PMID 19333441, 2009). "Loss of heterozygosity of 10q and 9p was present in the original glioblastoma, in the neurospheres and in tumors grown into mice, suggesting that PTEN and CDKN2A alterations are key genetic events in tumor initiating cells with neural precursor properties." (PMID 15469606, 2004). "Relationships between molecular alterations also emerged: notably, EGFR alterations were positively correlated with both CDKN2A/B and PDGFRA alterations in IDH1/2-mutant astrocytoma, reflecting the cooccurrence of canonical glioblastoma molecular alterations in these tumors." (PMID 39164213, 2025). "The incomplete activation of DREAM in glioblastoma cells following TMZ is very likely due to lack of CDKN2A/p16INK4A, which acts as specific inhibitor of CDK4/6-cyclin D." (PMID 41350483, 2025). "They reported that MTAP can identify CDKN2A status with 88% sensitivity and 98% specificity in astrocytoma Isocitrate dehydrogenase (IDH) mutant tumors, and 89% sensitivity and 100% specificity in glioblastoma, IDH-wildtype." (PMID 39409918, 2024).
glioblastoma (continued). "In glioblastoma (GBM), the progression may be associated with alterations in the Wnt, transforming growth factor beta (TGF-β), VEGF, EGFR, cyclin-dependent kinase 2A (CDKN2A), nuclear factor-κB (NF-κB), and phosphatidylinositol-3-kinase (PI3K)/AKT/mammalian target of rapamycin (mTOR) pathways." (PMID 39682237, 2024). "During glioblastoma (GBM), CDKN2A deletion remodels the GBM lipidome, notably redistributing oxidizable polyunsaturated fatty acids into distinct lipid compartments, and CDKN2A-deleted GBMs display higher lipid peroxidation, selectively priming tumors for ferroptosis." (PMID 37681908, 2023). "CNV plotting showed a homozygous CDKN2A loss and no other CNV findings consistent with glioblastoma." (PMID 31806041, 2019). "As is the case of METTL3 in glioblastoma, METTL14 depletion facilitates the malignant phenotype, characterized by upregulated oncogenes such as ADAM19 and reduced expression of tumor suppressors such as CDKN2A." (PMID 31921664, 2019). "Chromothripsis occurred in 29.3% glioblastomas (36/123) and mostly affected chromosomes 7, 9 and 12, with amplification of oncogenes (EGFR, MDM2/CDK4), and homozygous deletion of tumor suppressor genes (CDKN2A)." (PMID 30542515, 2018). "Furthermore, CDKN2A (1.20% of cases) and RB1 (1.03% of cases) are hallmarks of lung squamous cell carcinoma and glioblastoma respectively." (PMID 28155630, 2016). "Interestingly, among those genes we find the well-known glioblastoma oncogene EGFR and tumor suppressors CDKN2A and PTEN, but also novel candidates such as KRIT1 and PAOX described in the previous paragraph." (PMID 25679508, 2015). "Finally, future preclinical studies and clinical trials aimed at complementing MEK inhibitors with alternative modalities, such as radiation, immunotherapy, or targeted agents against comutated genes such as CDKN2A/B, will be critical to achieve durable responses in NF1-mutant glioblastomas." (PMID 40985888, 2025). "In addition to accompanying CDKN2A HD, there are also publications indicating that MTAP inactivation contributes to gliomagenesis through epigenetic mechanisms, especially in glioblastomas; thus, MTAP may be a target for treatment." (PMID 38109891, 2024). "In addition, the GTI identified 29 novel outlier genes in glioblastomas, including TYMS and CDKN2A." (PMID 21365010, 2011). "Several genes in the central glioblastoma pathways were identified through dramatic copy number alterations, such as amplification of the oncogenes, EGFR, c-MYC, CDK4, PDGFRA, MDM2, and MDM4, and deletion of the tumor suppressor genes, CDKN2A, CDKN2B, and PTEN." (PMID 21113414, 2010). "Interestingly, survClust identified a small IDH-mutant subtype characterized by CDKN2A deletion (c4) that showed markedly worse survival among the IDH-mutant tumors, similar to the IDH-WT group (c5) that tends to behave far more aggressively with prognosis similar to glioblastomas." (PMID 33272320, 2020).
glioblastoma (continued). "Targeted DNA sequencing identified CDKN2A/B homozygous deletion as a poor prognostic marker in somatic NF1-mutant, but not NF1 wild-type, glioblastoma." (PMID 40985888, 2025). "Targeted DNA sequencing of NF1-mutant, IDH wild-type glioblastomas (n = 186) identified CDKN2A/B homozygous deletion as a poor prognostic marker in NF1-mutant, but not NF1 wild-type, glioblastomas." (PMID 40985888, 2025). "In addition, we only conducted this study in a single GBM cell line and did not delve into the complex molecular pathways and downstream effectors by which CDKN2A exerts its tumor suppressor function in glioblastoma." (PMID 38438773, 2024). "In addition, CNV analysis showed focal deletions of CDKN2A/B and no other chromosomal aberrations consistent with IDH-wildtype glioblastomas were found." (PMID 33941250, 2021).